POLR3GL (RNA polymerase III subunit GL)
Description:
DNA-dependent RNA polymerase catalyzes the transcription of DNA into RNA using the four ribonucleoside triphosphates as substrates. Specific peripheric component of RNA polymerase III which synthesizes small RNAs, such as 5S rRNA and tRNAs.
Synonyms: flj32422; MGC3200; RPC32HOM; SOFM
Tractability: PROTAC: ubiquitination databases record sites on it; its protein half-life has been measured.
Gene: Protein-coding gene on chromosome 1 (145,964,690 to 145,978,848, forward strand). Ensembl gene ENSG00000121851.
Subcellular location: Nucleus
Pathways (Reactome):
Gene expression (Transcription): RNA Polymerase III Abortive And Retractive Initiation; RNA Polymerase III Chain Elongation; RNA Polymerase III Transcription Initiation From Type 1 Promoter; RNA Polymerase III Transcription Initiation From Type 2 Promoter; RNA Polymerase III Transcription Initiation From Type 3 Promoter; RNA Polymerase III Transcription Termination
Immune System: Cytosolic sensors of pathogen-associated DNA
Gene Ontology:
Molecular function: protein binding
Biological process: transcription by RNA polymerase III
Cellular component: nucleus; RNA polymerase III complex; cytosol; nucleoplasm
Genetic constraint (gnomAD): Loss-of-function variants: 23 observed, 29.64 expected, observed/expected ratio (o/e) 0.78, 90% interval 0.56 to 1.1. The upper end of that interval is the gene's LOEUF score, 1.1, which puts it in group 4 of 6, group 1 being the genes least tolerant of losing a copy. Missense variants: 200 observed, 233.97 expected, observed/expected ratio (o/e) 0.85, 90% interval 0.76 to 0.96. Synonymous variants: 88 observed, 84.68 expected, observed/expected ratio (o/e) 1.04, 90% interval 0.87 to 1.24.
Homologues: Orthologues: chimpanzee POLR3GL (99% identical), macaque POLR3GL (99% identical), dog POLR3GL (98% identical), rabbit POLR3GL (97% identical).
Diseases named in the same sentence as POLR3GL in open-access papers:
POLR3GL is named in the same sentence as 13 diseases in open-access papers, as found by Europe PMC text mining. Sharing a sentence is not in itself a finding about the gene and the disease. The quoted sentences say what the papers report.
acute myeloid leukemia (1 paper, 2023). Acute myeloid leukemia (AML) is a group of neoplasms arising from precursor cells committed to the myeloid cell-line differentiation. "This phenomenon is flipped for POLR3G and POLR3GL in acute myeloid leukemia (LAML), however, suggesting a potentially unique role of RPC7α and RPC7β in myeloid cells with implications for disease progression." (PMID 37894362, 2023).
breast carcinoma (1 paper, 2020). "—Downregulation of three (POLR3A, POLR3C, POLR3GL) catalytic components of RNA polymerase III, which synthesize small RNAs and were suggested as potential targets for breast cancer." (PMID 33302383, 2020).
leukodystrophies (1 paper, 2021). "Mutations in genes encoding subunits of the transcription complex RNA polymerase III (POLR3), namely POLR3A, POLR3B, POLR1C, POLR3K and POLR3GL might cause a particular type of hypomyelinating leukodystrophies known as Pol III-related leukodystrophies." (PMID 33804237, 2021).
prostate carcinoma (1 paper, 2019). A carcinoma that arises from epithelial cells of the prostate gland. "Depletion of POLR3G selectively triggers proliferative arrest and differentiation of prostate cancer cells, responses not elicited when POLR3GL is depleted." (PMID 30820548, 2019).
systemic lupus erythematosus (1 paper, 2025). An autoimmune multi-organ disease typically associated with vasculopathy and autoantibody production. "Given their absence in controls and potential functional relevance, and the limited prior research on their roles in SLE, we propose MXRA8, NADK, POLR3GL, and UBXN11 as candidate genes for further investigation in the context of systemic lupus erythematosus." (PMID 40777011, 2025).
Wiedemann-Rautenstrauch syndrome (1 paper, 2023). Wiedemann-Rautenstrauch syndrome is a very rare disorder with features of premature aging recognizable at birth, decreased subcutaneous fat, hypotrichosis, relative macrocephaly and dysmorphism. "Wiedemann-Rautenstrauch syndrome (neonatal progeroid syndrome) is an ultra-orphan disease from the group of premature aging syndromes with an autosomal recessive type of inheritance associated with mutations in the POLR3A, POLR3B, and POLR3GL genes encoding RNA polymerase III." (PMID 38796765, 2023).
cancer (4 papers, 2022 to 2025). A tumor composed of atypical neoplastic, often pleomorphic cells that invade other tissues. "POLR3G expression is generally restricted to the earliest stages of development but re-emerges in cancer, in contrast to more constitutive expression patterns observed for POLR3GL and genes encoding other Pol III subunits." (PMID 37894362, 2023). "In contrast, POLR3GL expression is the only signature strongly associated with favorable outcomes when analyzed across all cancer types." (PMID 36710885, 2022). "Here, we profiled the relationship between POLR3G (RPC7α) or POLR3GL (RPC7β) expression and outcomes among cancer patients, stratified by cancer subtype." (PMID 37894362, 2023). "Multiple reports have linked high POLR3G (RPC7α) expression with unfavorable outcomes across distinct cancer subtypes; however, few studies have directly compared clinical signatures associated with POLR3G, POLR3GL, or other Pol III subunits." (PMID 37894362, 2023). "The re-emergence of POLR3G expression in cancer and statistical relationship with unfavorable outcomes, in stark contrast to POLR3GL, is undeniable." (PMID 36710885, 2022). "Differences are observed in Pol III transcription in contexts overexpressing POLR3G or POLR3GL, and during differentiation-associated loss of POLR3G or re-emergence of POLR3G in cancer." (PMID 36710885, 2022). "The contrasting relationship between POLR3G and POLR3GL overexpression and cancer outcomes is, on its face, incongruous with a model in which both RPC7 subunits are functionally identical and raises questions about the regulation and function of Pol III identity in disease." (PMID 36710885, 2022). "In cancer, upregulation of POLR3G, but not POLR3GL, is associated with poor survival outcomes among patients, suggesting differences between RPC7α and RPC7β further influence disease progression and may translate into future biomarkers and therapeutic strategies." (PMID 36710885, 2022).
tumor (1 paper, 2022). "Specific overexpression of POLR3G but not of the paralogous POLR3GL subunit or any other component of the Pol III transcription system in TNBC is indicative of unique tumor-promoting functions of POLR3G in TNBC." (PMID 36497214, 2022).
POLR3GL also shares sentences with these, for which no sentence is quoted: diabetes (1 paper); glioma (1); Insulin resistance (1); neurological disorders (1); Type 2 Diabetes (1).